ESR1 (estrogen receptor 1)
Diseases named in the same sentence as ESR1 in open-access papers (continued):
Sharing a sentence is not in itself a finding about the gene and the disease.
cancer (continued). "Our study provides comprehensive evidence that ESR1, ESR2, and PGR are feasible prognostic markers and therapeutic targets for multiple cancers and that they could be a factor for disease prediction, disease evaluation, and individualized treatment in various types of cancer." (PMID 34322374, 2021). "Furthermore, though ESR1 mutant clones may be acutely sensitive to fulvestrant or the combination of palbociclib and fulvestrant, this does not translate into improved PFS for patients with ESR1 mutant cancers." (PMID 29497091, 2018). "There was also a significant (p < 0.05) negative correlation between ESR1 gene expression and IFITM2 expression levels in Luminal A cancer patients." (PMID 39765744, 2024). "Thus ESR1 deletions may contribute to the ER alpha negative status of these cancers." (PMID 35792986, 2022). "In our study cohorts, g3mclass automatically recognized cancers unlikely to be present in the reference, i.e., ERBB2 mRNA + (class 2 and higher) and ESR1 mRNA + (class 1 and higher)." (PMID 36335194, 2022). "OncoTree Code was selected to indicate the ratio of cancer patients with/without genetic alterations in ESR1, ESR2, and PGR, and results suggested the potentially critical roles of ESR1, ESR2 and PGR in onset of multiple cancers." (PMID 34322374, 2021). "Specifically, ESR1 and E2F1 were not correlated in the group with favorable prognosis, while they were significantly positively correlated in recurrent cancer." (PMID 33852600, 2021). "Other quantitative PCR analysis resulted in elevated expressions of ESR1, EGFR mRNA in cancer samples in comparison with those in non-cancer controls (P < 0.05)." (PMID 34592904, 2021). "With the exception of three clusters of NRs representing NR classes I (cluster I: RORC, VDR, PPARA, NR1D1, THRA, RORA, NR1H3; cluster II: RARB, PPARG, THRB) and III (cluster III: ESR1, PGR, AR, ESRRG), NR class was not a good determinate of NR expression patterns in the different cancer types." (PMID 32024906, 2020). "Interestingly, even no significant differential ESR1 and ESR2 expression were found in many carcinomas." (PMID 32536040, 2020). "Although no physiological E3 ligases for the estrogen receptor (ESR1) and ERBB2 ubiquitylation have yet been identified, this model could prove useful for understanding ERBB2-positive cancer." (PMID 19007432, 2008). "Consequently, EGFR was lowly expressed in the cancer group versus the normal group in LUAD without a statistical difference (P-value: 0.19) and this expression pattern was similar to ESR1 (P-value: 0.42), MYC (P-value: 0.067), RELA (P-value: 0.058) and SMAD3 (P-value: 0.13)." (PMID 33506873, 2021). "Interestingly, the ESR1/ESR2 ratio was characterized by a strong, negative correlation with ESR2/PELP1 ratio in OCP, and moderately strong with ESR2/SRC ratio in both benign changes of ovary and cancer affected tissue." (PMID 34207568, 2021). "In all 3 cancers, the signature scores had strong positive spearman correlations with the PLAU module (0.67 in pancreas, 0.40 in breast, 0.69 in ovarian) and relatively strong negative correlations with the ESR1 module (−0.51 in pancreas, −0.52 in breast, −0.35 in ovarian)." (PMID 31217513, 2019).
cardiovascular disease (57 papers, 2009 to 2025). "Estrogen receptor alpha (ESR1) gene polymorphisms were responsible for cardiovascular diseases." (PMID 26430422, 2015). "Various previous studies have proven that the abnormal expression of ESR1, which had the highest value in our PPI network, was closely associated with cardiovascular diseases." (PMID 32880387, 2020). "A large body of evidence supports the impact of estrogen receptor alpha (ESR1), which regulates the expression of multiple genes after activation by estrogen, in cardiovascular disease in both men and women." (PMID 21658281, 2011). "The ESR1 gene promoter TA repeats were classified as short (≤18 TA repeats, 160-176 bp) and long (≥19 TA repeats, 178-194 bp), corresponding to their bimodal distribution and in accordance with previous studies on cardiovascular diseases and non-cardiovascular diseases." (PMID 24577825, 2014).
adenocarcinoma (56 papers, 2008 to 2026). A common cancer characterized by the presence of malignant glandular cells. "Previous studies have shown that abnormal methylation patterns of genes (APC, CdH1, CDKN2A, and ESR1) are not only limited to adenocarcinoma tissues but also found in precancerous BE tissues." (PMID 34222478, 2021).
infection (45 papers, 2011 to 2025). The state of being infected such as from the introduction of a foreign agent such as serum, vaccine, antigenic substance or organism. "The compound was concentrated in vesicle-like structures during late infection so that the target could be the ESR1 and NS1 proteins." (PMID 34834059, 2021). "At day 9 post-infection, network 2 illustrated interactions between several miRNAs and genes such as CTNNB1, SMARCA4, and ESR1." (PMID 41157560, 2025). "In summary, the cellular ESR1 and viral NS1 were suggested as possible targets during late infection." (PMID 34834059, 2021). "The network analysis, homopharma, and molecular docking revealed that the estrogen receptor 1 and viral NS1 were potential targets at the late infection stage." (PMID 34834059, 2021). "(d) Mean ± SEM days/week in proestrus before (from day −12 to day 14) and after infection (day 29 to day 56) in mice receiving Arc-AAV-lacZ, -Esr1 g1 or g2." (PMID 30946012, 2019). "In summary, the alkyne-tagged apigenin could represent the ESR1 and NS1 as potential targets of the apigenin during late infection based on the molecular docking study." (PMID 34834059, 2021). "At the first stage of infection, SLC25A6, which has low acetylation activity and DNA methylation activity (p-value = 1.14 × 10−2), is repressed by human miR1244-1 and reduces transcriptional regulation via TFs, ESR1 and MYC." (PMID 30133498, 2018). "While HSV2 did increase ER-alpha protein, infection did not change ESR1 mRNA (analysis of variance (ANOVA), n.s.), suggesting protein stabilization as opposed to increased transcription." (PMID 29190738, 2017). "Sex differences in lung-resident cDCs during infection have not been reported, but these DCs do express Esr1 suggesting estrogens may regulate their important role in initiation of innate and adaptive responses to viruses." (PMID 30079065, 2018). "However, a slight decrease ESR1 expression could be observed in testosterone treated female mice irrespective of infection." (PMID 32431696, 2020). "Also the expression of transcription factors was significantly modified by HHV-6A/6B infection, with an early increase of ATF3, JUN and FOXA2 by both species, whereas HHV-6A specifically induced a 15-fold decrease of POU2AF1, and HHV-6B an increase of FOXO1 and a decrease of ESR1." (PMID 29163428, 2017).
metabolic disease (32 papers, 2008 to 2025). A congenital disorder (due to inherited enzyme abnormality) or acquired (due to failure of a metabolically important organ) disorder resulting from an abnormal metabolic process. "In this data article, we investigated whether metabolic disorders in Esr1 knockout (Esr1-/-) male rats were linked with loss of transcriptional regulation by ESR1 in liver." (PMID 30671521, 2019). "An imbalance between ESR1 in the adipose tissue could therefore affect the development of metabolic diseases." (PMID 34858323, 2021). "The ESR1 and ESR2, which are involved in the estrogen signaling pathway, are highly related to menopause-related metabolic diseases." (PMID 31752216, 2019). "An imbalance between ESR1 and ESR2 in the adipose tissue could therefore affect the development of metabolic diseases." (PMID 30217154, 2018).
benign tumors (17 papers, 2012 to 2025). "The benign tumors displayed characteristics in line with their PAM50 subtype, both with regards to proliferation, ESR1 expression, mutations and copy number aberrations." (PMID 35932380, 2022). "Mammary hyperplasia/dysplasia of FFPE samples exhibited significantly higher expression of ESR1 than benign tumors (p = 0.005)." (PMID 27649560, 2016). "The borderline and benign tumors on the other hand correlated to the ESR1/ER signaling module." (PMID 25226589, 2014). "Compared with miRNA expression levels, an opposite trend in the expression pattern of the ESR1 target gene was observed in this study, with a significantly lower expression of ESR1 mRNA in malignant CMTs compared with both the non-neoplastic mammary gland and benign tumors." (PMID 36978627, 2023).
psychiatric disorder (14 papers, 2016 to 2025). A disorder characterized by behavioral and/or psychological abnormalities, often accompanied by physical symptoms. "In particular, ESR1 has been implicated in psychiatric disorders, and YWHAG is known to modulate multiple signaling pathways relevant to mood regulation." (PMID 41325417, 2025). "In searching for functional variants, we therefore have to consider the target tissue (brain regions in this study), sex, age, and psychiatric disorders, to reflect possible dynamic interactions with regulatory variants on ESR1 expression." (PMID 28617822, 2017).
neurological disorders (10 papers, 2009 to 2024). "Here we assert that ESR1 is a key gene linking endocrine disease and neurological disease." (PMID 19779549, 2009).
gastrointestinal tumors (7 papers, 2017 to 2025). "Interestingly, a high correlation was observed among AR, ESR1, and PGR genes in gastrointestinal tumors (COAD, READ, and STAD) as they may play a synergistic role in these tumors." (PMID 32536040, 2020).
gynecological disease (5 papers, 2013 to 2024). "Mutations in the ESR1 gene that encodes for ERα, which were shown to also affect signaling pathways involved in inflammation, further indicate its importance in gynecological disease prognosis." (PMID 38927277, 2024). "The role of the ESR1 gene in the pathogenesis of UFs and other gynecologic diseases has been reported." (PMID 36890612, 2023).
heart disease (5 papers, 2017 to 2024). "ESR1, the second most significant gene, was reported to be related to fear conditioning and heart diseases." (PMID 29322921, 2017).
gynecologic tumors (4 papers, 2014 to 2026). "Gynecologic tumors harbored ESR1 alterations that have prognostic and potentially therapeutic relevance." (PMID 41555446, 2026).
ESR1 also shares sentences with these, for which no sentence is quoted: Glucose intolerance (32 papers); glioblastoma (28); breast (26); neurodegenerative disease (22); papillary thyroid carcinoma (22); pituitary tumor (20); ischemia (18); lobular carcinoma (18); multiple sclerosis (15); squamous cell carcinoma (15); Cerebral ischemia (14); colitis (14); Gynecomastia (14); meningioma (14); steatosis (14); experimental autoimmune encephalomyelitis (12); lobular breast cancer (12); lung squamous cell carcinoma (12); kidney disease (11); serous carcinomas (11); astrocytomas (10); bladder tumors (10); renal cell carcinoma (10); chronic myeloid leukemia (9); gastric tumor (9); memory impairment (9); renal carcinoma (9); uterine sarcomas (9); endometrioid tumor (8); glomerulosclerosis (8).
A further 550 diseases each share a sentence with ESR1 in 8 papers or fewer.